CCL19 (C-C motif chemokine ligand 19)
Diseases named in the same sentence as CCL19 in open-access papers (continued):
Sharing a sentence is not in itself a finding about the gene and the disease.
lymphoma (continued). "As CCL19, the ligand of CCR7, promotes the development of PCNSL through the retention of CCR7 expressing lymphoma cells in the brain, the CCR7-CCL19 axis might also play a role in the evasion of malignant B cells from the brain to the CSF." (PMID 36153593, 2022). "It has been uncovered that compared with conventional CD19 CAR-T cells, the combination of IL7 and CCL19 can promote the infiltration, accumulation, and survival of CAR-T cells in lymphoma tissues, further enhancing the antitumor effect of conventional CAR-T cells." (PMID 36189258, 2022). "Combining the CCR7 expression with the CCL19 and CCL21 expression pattern, it seems that CCR7 signaling is altered in the lymphoma setting compared to the non-neoplastic condition." (PMID 35887224, 2022).
atherosclerosis (17 papers, 2010 to 2025). A disease characterized by the build-up of fatty material and calcium deposition in the arterial wall resulting in partial or complete occlusion of the arterial lumen. "Upregulation of RGS1 in peripheral blood T lymphocytes decreased their chemotactic response to CXCL12 and CCL19, both implicated in atherosclerosis." (PMID 32443695, 2020). "In general, our research demonstrated that IRF-1 and CCL19 are involved in the course of atherosclerosis, which may be used as diagnostic markers and new therapeutic targets." (PMID 33424012, 2020). "CCL2 and CCL5 are primarily involved in monocyte and SMC recruitment, promoting the formation of atherosclerosis, whereas CCL19 and CCL21 facilitate macrophage emigration, thereby promoting the regression of advanced plaques." (PMID 40236901, 2025). "CCL19 mRNA has also been observed in human atherosclerotic lesions proposing it has a role in atherosclerosis." (PMID 33503867, 2021). "The expression of CCR7 in macrophage is essential for decreasing the macrophage amount in plaques and promoting the regression of atherosclerosis, by interacting with its specific ligands CCL19 and CCL21." (PMID 34345249, 2021). "In intimal medullary cells, reverse transendothelial migration dependent on CCR7 and CCL19 protect normal arterial intima during atherosclerosis." (PMID 33424012, 2020). "Chemokine ligand 19 (CCL19) has been reported highly expressed in peripheral blood of patients with atherosclerosis, but its role lacks explicit data." (PMID 33424012, 2020). "The upregulation of key proteins such as IL-6, CXCL10, and CCL19 suggests an inflammatory signature in OBO individuals that may promote atherosclerosis along with other upregulated pro-inflammatory cytokines activating monocytes." (PMID 40076884, 2025). "Moreover, CCL19 has been studied in relation to its effects on endothelial dysfunction and atherosclerosis, which are common complications of T2DM." (PMID 39574905, 2024). "CCL21 and CCL19, chemokines involved in vascular inflammation and atherosclerosis, might be modulated by CARMN to regulate immune cell behavior affecting VSMCs." (PMID 38597937, 2024). "Interferon regulatory factor 1 (IRF-1) contributes to the pathological phenotype of VSMCs during atherosclerosis by increasing CCL19 transcription, whereas silencing IRF-1 inhibits angiotensin proliferation and migration and downregulates CCL19 expression, thereby suppressing atherosclerosis." (PMID 36720935, 2023). "CCL19, as one of the cytokines, could regulate the inflammation and matrix remodeling in atherosclerosis and rheumatoid arthritis." (PMID 35722091, 2022). "In order to investigate the role of CCR7/CCL19/CCL21 in atherosclerosis progression, the plaque-containing arterial segments from apo E-deficient mice were transplanted into the wild-type recipient normolipidemic mice to induce an atherosclerosis regression." (PMID 34345249, 2021). "Firstly we verified that CCL19 highly expressed in patients with atherosclerosis." (PMID 33424012, 2020). "The role of CCL19 and CCL21 in experimental atherosclerosis in mice is still disputed as results from different studies are contradictory." (PMID 33503867, 2021). "Increased levels of CCL19 and CCL21 in atherosclerosis can lead to changes in T-cell and macrophage responses by regulating dysfunction, thus reducing plaque stability and contributing to atherosclerosis development." (PMID 40535169, 2025). "CCL19 and CCL21 are expressed on macrophages and synovial fibroblasts and have also been reported to be elevated in the sera of patients with chronic inflammatory diseases, such as RA and atherosclerosis." (PMID 38711500, 2024). "Thus, CCL19 is involved in vascular remodeling in atherosclerosis, by inducing VSMC proliferation and enhancing protein expression of MMP-1 in VSMCs, which acts to destabilize the plaques, while both CCL19 and CCL21 foster macrophage foam cell formation." (PMID 35600479, 2022).
atherosclerosis (continued). "However further research is required in vivo to determine the CCL19/CCL21/CCR7 role in the recruitment and infiltration of monocytes in atherosclerosis and to determine its therapeutic potential." (PMID 33503867, 2021). "A clinical study demonstrated that CCL19 and CCL21 was up regulated in carotid atherosclerosis in 158 patients compared to a control of 20 patients, suggesting an important role for these chemokines in atherosclerosis." (PMID 33503867, 2021). "Importantly, silencing IRF-1 inhibited atherosclerosis in high-fat-fed mice, inhibited the proliferation and migration of VSMCS, and down-regulated the expression of CCL19." (PMID 33424012, 2020). "In the present study, we observed that patients with CAS had significantly elevated serum levels of CX3CL1, CXCL12, CCL19, CCL21, CCL2, and CCL5 compared to control individuals, suggesting that these chemokines are intricately involved in the initiation and progression of atherosclerosis." (PMID 40236901, 2025). "We previously showed increased levels of CCL19 and CCL21 in coronary artery disease, and it may be argued that the raised levels of these mediators in HF merely reflect that several of these patients also have accompanying atherosclerosis." (PMID 22427939, 2012).
rheumatoid arthritis (16 papers, 2007 to 2025). A chronic, systemic autoimmune disorder characterized by inflammation in the synovial membranes and articular surfaces. "In rheumatoid arthritis, it has been reported that the activation of CCL19/CCL21-CCR7 signaling pathway increases the infiltration of M1 macrophages." (PMID 36684607, 2022). "It reported that CCL19 and the paired CCR7 were are associated with autoimmune diseases like rheumatoid arthritis and enteropathy." (PMID 34046056, 2021). "The upregulation of CCL19 and CCL21 and their receptor CCR7 was associated to Rheumatoid arthritis pathogenesis, playing an important role in bone destruction by increasing osteoclast migration and resorption activity." (PMID 31888477, 2019). "They found that in rheumatoid arthritis patients, CCL19 levels were significantly upregulated in synovial tissues compared with normal tissues." (PMID 25401103, 2014). "In patients with rheumatoid arthritis, CCL19 may reflect blood B cell disturbances and predict clinical responses to rituximab (RTX)." (PMID 31068931, 2019). "CCL19 maybe involved in more sever forms of autoimmune diseases, such as rheumatoid arthritis." (PMID 34367157, 2021). "The factors driving TLS generation are complex; for example, fibroblasts in the tissues of rheumatoid arthritis produce lymphochemokines such as CXCL13, CCL19, and CCL21, which are involved in TLS formation." (PMID 40718780, 2025). "Lee and collaborators (2017) have shown that treatment with IL-1β and TNF-α raised CCR7 expression in both precursors and differentiated osteoclasts, increasing their migratory activity toward CCL19 and CCL21 chemokines upregulated in rheumatoid arthritis." (PMID 36831188, 2023). "CCL21 expression is upregulated in rheumatoid arthritis wherein CCL21 is the critical CCR7 ligand mediating migration, whereas CCL19 is redundant." (PMID 28474508, 2017). "The ligands CCL19 and CCL21, and their receptor CCR7 have been found to be involved in homing of lymphocytes to the target organ and to be localized in the lymphocytic infiltrates of the synovium in patients with rheumatoid arthritis." (PMID 17900348, 2007).
Obesity (13 papers, 2012 to 2025). Accumulation of substantial excess body fat. "Our data indicate that besides CCL2 and CCL5, numerous other chemokines such as CCL19 are expressed by adipocytes under obesity-associated chronic inflammation." (PMID 23824685, 2013). "Moreover, a recent study has documented elevated CCL19 levels in correlation with CRP among individuals with obesity, indicating a potential association with systemic inflammation." (PMID 40076884, 2025). "The CCL19/CCR7 pathway promotes the progression of high-fat-induced IR and obesity, and these issues are well-known as risk factors for accelerating the pathogenesis of NAFLD and AS." (PMID 37063958, 2023). "CCL19 is a chemokine expressed in adipose tissues that is believed to play an important role in low-grade inflammation observed in obesity by recruiting macrophages to those tissues." (PMID 30242179, 2018). "In addition, CCL19 mediates diet-induced obesity and insulin resistance, and epicatechin decreases CCL19 expression in adipose tissue and inhibits diet-induced obesity and insulin resistance." (PMID 35222545, 2022). "Inflammatory markers, including CD16, CD11c, CCR2, CCR5, TNF-α, IL-1β, IL-2, IL-12, CCL8, CCL19, and CXCL9, were positively correlated with IL-23 in the AT-compartment in the obesity context." (PMID 41158638, 2025). "Additionally, a study has also shown that the pathway formed by the CCL19 gene and its receptor CCR7 plays a key role in inducing obesity and insulin resistance." (PMID 35812876, 2022). "Notably, significant elevations in IL-2 expression in the AT together with that of other inflammatory mediators (IL-8, IL-12A, CCL5, CCL19, CCR2 and CCR5 and TLRs) in obesity suggests that these factors may contribute cooperatively for insulin resistance induction in this population." (PMID 33004937, 2020).
pancreatic cancer (13 papers, 2015 to 2025). "A phase 1 clinical trial (NCT03198546) evaluating CAR-T cells with constitutive expression of IL-7 and CCL19 in six patients with progressive hepatocellular carcinoma, pancreatic carcinoma, and ovarian carcinoma expressing either GPC3 or MSLN showed promising results." (PMID 41154636, 2025). "In another study, the intravenous injection of interleukin 7 (IL-7) and Chemokine (C-C motif) ligand-19 (CCL19)-MSLN secreting CAR-T cells (NCT03198546) in a patient with advanced pancreatic cancer induced complete regression of the tumor 240 days post-treatment." (PMID 36717905, 2023). "The goal of this study is to apply the IL7/CCL19‐producing technology to make anti-EGFRvIII or HER2 CAR-T more offensive to glioblastoma and pancreatic cancer, so as to improve the therapeutic efficacy." (PMID 39240078, 2024). "This study explored the therapeutic potential and immunologic mechanisms of IL7/CCL19-producing CAR-T therapy in preclinical solid cancer models of glioblastoma and pancreatic cancer." (PMID 39240078, 2024). "In reference to IL-7/CCL19-engineered mesothelin-redirected CAR-Ts, it was reported that the adoptive transfer of these CAR-Ts to a pancreatic cancer patient led to the complete elimination of tumors almost 8 months following CAR-T treatment." (PMID 38146364, 2023). "It was found that tumors from hepatocellular carcinoma, colorectal or pancreatic cancer patients produced IL-8; a chemokine that attracts DCs and that blocks their migration towards MIP-3β (CCL19), a cytokine that draws DCs to lymphoid organs." (PMID 25682197, 2015). "In summary, this study revealed that the IL7/CCL19 production technology confers potent antitumor efficacy on CAR-T targeting EGFRvIII or HER2 and can be applicable to CAR-T against intractable solid cancers such as glioblastoma and pancreatic cancer." (PMID 39240078, 2024). "Moreover, these researchers reported that adoptive transfer of their IL-7/CCL19-engineered CAR-Ts mediated strong tumor regression in xenograft models of liver cancer and pancreatic cancer." (PMID 38146364, 2023). "Another ongoing clinical trial (NCT03932565) evaluates intratumoral injection of Nectin4/FAP-targeted fourth-generation CAR-T cells (expressing IL-7 and CCL19, or IL12) for the treatment of Nectin4-positive advanced malignant solid tumors (NSCLC, breast, ovarian, bladder or pancreatic cancer)." (PMID 35211124, 2022). "The same team validated the use of anti-mesothelin IL-7/CCL19-producing human CAR-T cells in a preclinical model of orthotopic pre-established malignant mesothelioma, as well as in patient derived xenograft (PTX) models of mesothelin-positive pancreatic cancer." (PMID 35211124, 2022). "Unfortunately, CCL19 expression was not evaluated in this study; however, the available data suggests that CCR7, presumably activated by CCL19, allows for pancreatic cancer metastasis to lymphoid tissue." (PMID 35203305, 2022).
autoimmune disease (11 papers, 2014 to 2025). A disorder resulting from loss of function or tissue destruction of an organ or multiple organs, arising from humoral or cellular immune responses of the individual to their own tissue constituents. "In these autoimmune diseases, CCL19 often acts as a pathogenic inflammatory factor in the disease mechanisms." (PMID 40726550, 2025). "We also detect and characterize tertiary lymphoid structures marked by CXCL13/CXCR5 and CCL19-mediated signaling from Tph cells and immunoregulatory DCs, analogous to those observed in other autoimmune diseases." (PMID 41269758, 2025). "We also detect and characterize tertiary lymphoid structures marked by CXCL13–CXCR5 and CCL19-mediated signaling from Tph cells and immunoregulatory dendritic cells, analogous to those observed in other autoimmune diseases." (PMID 40894156, 2025). "Some studies link CCL19 with inflammation in autoimmune diseases, but there is limited information regarding its role in AIH." (PMID 37108648, 2023). "Collectively, these results suggest that the CCL19/CCR7 axis plays an important role in the progression of autoimmune diseases and is closely related to immune regulation at the site of the lesion." (PMID 35702353, 2022). "Blocking the CCL19/CCR7 axis is a potential therapeutic option for the treatment of autoimmune diseases." (PMID 35702353, 2022). "The up-regulation of CCL19 was also observed in patients with primary and secondary SS compared to another autoimmune disorder or control, and was considered to contribute to the leukocyte microenvironmental homing in MSG from SS patients." (PMID 31068931, 2019). "This indicates that the balance of CCL19 levels plays a crucial role in autoimmune diseases." (PMID 40726550, 2025). "However, CCL19 has been widely studied in other autoimmune diseases, such as RA, SLE, and multiple sclerosis." (PMID 40726550, 2025). "CCL19 plays a role in trafficking of lymphocytes to secondary lymphoid organs as well as to tertiary lymphoid structures such as those that occur in target organs in the context of several autoimmune diseases." (PMID 30347820, 2018). "The intrathecally produced CCL19 might not only play a role in inducing autoimmune diseases but also in maintaining chronic forms through recruitment of antigen presenting cells and lymphocytes, resulting in perpetual antigenic stimulation." (PMID 25016392, 2014).
ovarian carcinoma (11 papers, 2022 to 2025). A malignant neoplasm originating from the surface ovarian epithelium. "For patients from multiple independent cohorts, suppressed CCL19 expression exerts significant progressive phenotype and apoptosis activity of cancers, especially in breast and ovarian cancer." (PMID 37944262, 2023). "This suggests the potential of CCL19 as a prognostic marker and immunotherapy target in breast and ovarian cancers." (PMID 37944262, 2023). "In cancer biology, local production of CCL19 promotes antitumor responses by recruiting more CD8+ T cells in lung and ovarian cancer models." (PMID 39190494, 2024). "SNAI2/Slug, and SNAI1/Snail have been reported to be upregulated by treatment with TGF-β and BMP as well as by treating ovarian cancer cells with IL-17, chemokine CCL5, and CCL19/CXCR7." (PMID 36766756, 2023). "The second one, cited earlier, is a phase I clinical trial (NCT03932565) using fourth-generation CAR-T cells coproducing IL-7 and CCL19/IL-2 in patients with Nectin4-positive advanced malignant solid tumors such as NSCLC, breast, bladder, pancreatic and ovarian cancer." (PMID 35211124, 2022).
hepatocellular carcinoma (9 papers, 2015 to 2025). A malignant tumor that arises from hepatocytes. "NCT03198546 is a phase 1 trial testing the safety and efficacy of anti-GPC3-7 × 19 CAR-T cells (GPC3 CAR-T cells to secrete human IL-7 and CCL19) in patients with advanced hepatocellular carcinoma (HCC) expressing GPC3." (PMID 37371075, 2023). "We found that the expression of CCL19 in CTNNB1 wild-type hepatocellular carcinoma cells (HepG2 cells) is higher than that in CTNNB1 mutant cells (Huh6 and SNU398 cells)." (PMID 36189258, 2022).
Insulin resistance (9 papers, 2019 to 2025). Increased resistance towards insulin, that is, diminished effectiveness of insulin in reducing blood glucose levels. "In support of this argument, TNF-α, IL-6, IL-8, CCL2, CCL4, CCL5, and CCL19 were found to be implicated with metabolic inflammation or insulin resistance in various tissues and organs." (PMID 31718015, 2019). "CCL19 is associated with T2DM through its role in promoting inflammation, contributing to insulin resistance, and possibly aggravating cardiovascular complications." (PMID 39574905, 2024). "Noticable beneficial effects of EC for the prevention of adipose tissue inflammation and insulin resistance by marked suppression of CCL19." (PMID 36359402, 2022). "The expression of the CCL19 gene is increased in obese human adipose tissue and is positively correlated with markers of insulin resistance and metabolism, indicating that CCL19 may be an essential marker for predicting insulin resistance and metabolism." (PMID 35812876, 2022). "• T cell activation. • Induction of inflammatory molecules like IL8, IL12A, CCL5, CCL19, CCR2, and CCR5. • Contribution to increased insulin resistance secondary to TLR2, TLR4, and TLR10 interaction." (PMID 35422689, 2022).